MTUS1 (microtubule associated scaffold protein 1)
Diseases named in the same sentence as MTUS1 in open-access papers (continued):
Sharing a sentence is not in itself a finding about the gene and the disease.
bladder cancer (5 papers, 2014 to 2023). "Reduced MTUS1 expression is also associated with poor prognosis in lung adenocarcinoma, gallbladder adenocarcinoma, renal cell carcinoma, bladder carcinoma, adenoid cystic carcinoma of the salivary gland, and squamous cell carcinoma of the tongue." (PMID 36980447, 2023). "MTUS1 downregulation or loss has been documented in many types of cancer, including colon, oral, gastric, and bladder cancer." (PMID 28364280, 2017). "In the meantime another study group also found an association between MTUS1 expression and bladder cancer." (PMID 24650297, 2014). "We further want to reveal the reason for the frequent loss of MTUS1/ATIP in bladder cancer and the differences between papillary, micropapillary and other advanced bladder cancers." (PMID 24650297, 2014). "Although MTUS1/ATIP loss was detected in approximately 50% of all investigated bladder cancers, there was only a significant association with worse OS and DSS in advanced bladder carcinomas, but not in papillary bladder carcinomas." (PMID 24650297, 2014). "Although we could find complete loss of MTUS1 protein expression in almost 50% of the cases in both bladder tumour cohorts, survival was only influenced in the advanced bladder cancer group." (PMID 24650297, 2014). "Here expression loss was associated with worse OS and DSS, indicating that MTUS1 acts as a classical tumour suppressor gene and that it might be a new target gene at chromosome 8p as well as an independent prognostic factor in advanced bladder cancer." (PMID 24650297, 2014). "In our study we searched for new target genes in the critical chromosomal region 8p and investigated the potential tumour suppressor gene candidate MTUS1/ATIP in bladder cancer." (PMID 24650297, 2014). "In summary, MTUS1/ATIP was identified as a tumor suppressor gene in cultured bladder cancer cells and in patients with advanced bladder cancers." (PMID 24650297, 2014). "This study revealed equally, that MTUS1 is an independent prognostic factor for DSS in bladder cancer." (PMID 24650297, 2014). "To clarify its role in bladder cancer, we further analysed MTUS1 in cell culture and immunohistochemical experiments." (PMID 24650297, 2014). "MTUS1 is a tumour suppressor gene in cultured bladder cancer cells and in advanced bladder tumours." (PMID 24650297, 2014). "MTUS1 protein expression was lost in almost 50% of all papillary and advanced bladder cancers." (PMID 24650297, 2014). "In addition to our findings, one recently released study found a correlation of reduced MTUS1 mRNA expression with poor prognosis in bladder cancer patients." (PMID 24650297, 2014). "As there was no known association between MTUS1 and bladder cancer during time of analysis, we selected this gene for further characterization." (PMID 24650297, 2014). "For bladder cancer, however, no mutation analysis data for MTUS1 is available yet." (PMID 24650297, 2014). "We screened four bladder cancer cell lines (RT112, RT4, J82 and BFTC905) as well as two presumably normal and immortalized urothelial cell lines, UROtsa and HCV29, for MTUS1 mRNA expression using qRT-PCR." (PMID 24650297, 2014). "However, MTUS1 expression did not influence survival and thus does not seem to be important for prognosis or disease progression in the papillary pathway of bladder cancer development." (PMID 24650297, 2014).
colon cancers (5 papers, 2012 to 2024). "As recently shown by our group, MTUS1 is down-regulated in 50% of the investigated colon cancers and MTUS1 siRNA transfection in HUVEC cells results in significant increased cell proliferation." (PMID 22200760, 2012).
head and neck squamous cell carcinoma (5 papers, 2016 to 2026). A squamous cell carcinoma that arises from any of the following anatomic sites: lip and oral cavity, nasal cavity, paranasal sinuses, pharynx, larynx, and salivary glands. "We showed that microtubule-associated tumor suppressor gene (MTUS1/ATIP) downregulation correlated with poor survival in head and neck squamous cell carcinoma (HNSCC) patients and that MTUS1/ATIP1 was the most abundant isoform in HNSCC tissue." (PMID 38725862, 2024).
lymph node metastasis (5 papers, 2016 to 2023). "In our study of lung adenocarcinoma patients, low MTUS1 expression was significantly associated with larger tumor size, higher T stage, lymph node metastasis, higher AJCC stage, worse histologic grade, lymphovascular invasion, and higher Ki-67 proliferation index." (PMID 34359333, 2021). "Low level of MTUS1 was significantly associated with higher clinical stage (p = 0.006), higher tumor stage (p = 0.044), lymph node metastasis (p = 0.01), worse histologic grade (p = 0.007), lymphovascular invasion (p = 0.014), and higher Ki-67 proliferation index (p < 0.001)." (PMID 34359333, 2021). "Specifically, low MTUS1 expression was associated with clinicopathological parameters related to cancer proliferation (tumor size and Ki-67 proliferation index) and metastasis (lymphovascular invasion and lymph node metastasis) in our study." (PMID 34359333, 2021). "In final part of present study, we observed a strong association between SIRT3, SIRT4, MTUS1 and OGG1-2a gene expression and lymph node metastasis." (PMID 26785117, 2016). "Low MTUS1 protein expression is closely correlated with poor prognostic clinicopathological parameters, including larger tumor size, higher histological grade, lymphovascular invasion, perineural invasion, and lymph node metastasis." (PMID 36980447, 2023). "In lung adenocarcinoma tissues, low MTUS1 expression is related to various clinical-pathological parameters, such as tumour size, Ki-67 proliferation index, lymphovascular invasion, and lymph node metastasis, which lead to the correspondingly poor prognosis of patients." (PMID 35962436, 2022). "Compared to the high-expression group, the low-expression group for MTUS1 protein showed significantly larger tumor size (p = 0.047), worse histological grade (p < 0.001), more lymphovascular (p < 0.001) and perineural (p = 0.047) invasion, and lymph node metastasis (p < 0.001)." (PMID 36980447, 2023).
head and neck cancer (4 papers, 2009 to 2022). A primary or metastatic malignant neoplasm affecting the head and neck. "The results showed that the expression of MTUS1 was higher in head and neck cancer, kidney cancer, lymphoma, myeloma, and other cancer tissues than in normal tissues." (PMID 35962436, 2022). "We and others have also identified MTUS1 gene variations located on ATIP3-specific exons in head-and-neck carcinoma cell lines." (PMID 19794912, 2009). "The present study was designed to study the expression pattern of selected mitochondrial tumor suppressor genes in head and neck cancer and to investigate the association of SIRT 3, SIRT4 and MTUS1 gene expression with the clinical characteristics and prognosis of head cancer patients." (PMID 26785117, 2016). "However, the implications of mitochondrial tumor suppressor genes SIRT3, SIRT4 and MTUS1 in head and neck cancer are largely unknown." (PMID 26785117, 2016).
pancreatic cancer (4 papers, 2012 to 2021). "Consistent with the initial report that MTUS1 may be a candidate tumor suppressor gene in pancreatic cancer, inactivation of the gene in knock-out animals was associated with B cell lymphoproliferative disease." (PMID 34062782, 2021). "Investigations on MTUS1, which is located at chromosome 8p21.3–22 and ubiquitously expressed, showed that MTUS1 mRNA was down-regulated in fast proliferating pancreas carcinoma cell lines, while recombinant expression of MTUS1 reduced cellular proliferation significantly." (PMID 22200760, 2012).
breast tumors (3 papers, 2009 to 2021). "We show that ATIP3 is the major MTUS1 splice variant whose expression is significantly reduced in invasive breast tumors of high histological grade and triple-negative phenotype." (PMID 19794912, 2009). "However, strategies for targeting ATIP3-deficiency in breast tumors still require better knowledge of epigenetic mechanisms involved in MTUS1 gene alterations in cancer." (PMID 34062782, 2021). "In line with these molecular data, human breast tumors expressing low MTUS1 levels were shown to exhibit elevated aneuploidy and chromosome instability." (PMID 34062782, 2021).
clear cell renal cell carcinoma (3 papers, 2020 to 2022). "Another mechanism for regulation of MTUS1 mRNA stability by the RNA binding protein SORBS2 was recently reported in clear cell renal cell carcinoma." (PMID 34062782, 2021).
lung adenocarcinoma (3 papers, 2021 to 2023). A carcinoma that arises from the lung and is characterized by the presence of malignant glandular epithelial cells. "MTUS1 is also associated with poor prognosis in patients with lung adenocarcinoma, gastric cancer, renal cell carcinoma, gallbladder carcinoma, salivary adenoid cystic carcinoma, and oral tongue squamous cell carcinoma." (PMID 35962436, 2022). "Despite these limitations, our data demonstrated strong associations of MTUS1 expression level with established poor prognostic factors and survival in lung adenocarcinoma patients." (PMID 34359333, 2021). "In this study, we investigated MTUS1 expression by immunohistochemical staining and its association with clinicopathological factors in 161 lung adenocarcinoma patients." (PMID 34359333, 2021). "This study investigated the clinicopathological significance of MTUS1 expression in lung adenocarcinoma." (PMID 34359333, 2021). "Analysis of data from the TCGA confirmed that the mRNA expression of MTUS1 in lung adenocarcinoma was significantly lower than that of normal lung tissue (p = 0.02)." (PMID 34359333, 2021). "In fact, in the TCGA lung adenocarcinoma data, some cancer tissue exhibited higher MTUS1 expression than in normal tissues." (PMID 34359333, 2021). "The precise role and clinical significance of MTUS1 in lung adenocarcinoma are unclear." (PMID 34359333, 2021). "Our findings are also consistent with results from the TCGA dataset, which showed lower MTUS1 mRNA expression in lung adenocarcinoma tissues compared with that of normal lung tissues and demonstrated shorter overall survival in lung adenocarcinoma patients with lower MTUS1 expression." (PMID 34359333, 2021). "Analysis of data from the Cancer Genome Atlas confirmed that the mRNA expression of MTUS1 in lung adenocarcinoma was significantly lower than that of normal lung tissue (p = 0.02), and patients with decreased MTUS1 expression showed significantly shorter overall survival (p = 0.008)." (PMID 34359333, 2021). "Our findings are consistent with results from studies of other human cancers and suggest that MTUS1 as a tumor suppressor may also play a crucial role in lung adenocarcinoma, with the potential to serve as a novel biomarker for lung adenocarcinoma patients, especially in early stages." (PMID 34359333, 2021).
oral cancer (3 papers, 2009 to 2026). "MTUS1 expression was consistently lower in cisplatin-resistant oral cancer cell lines than in their paired cisplatin-sensitive counterparts." (PMID 42161419, 2026). "MTUS1 messenger RNA and protein levels were examined in cisplatin-sensitive oral cancer cell lines and their paired cisplatin-resistant counterparts using quantitative reverse transcription polymerase chain reaction and western blotting." (PMID 42161419, 2026). "The Mitochondrial Tumor Suppressor (MTUS1) gene is an interesting candidate whose expression is reduced in colon, pancreas, ovary and oral cancers." (PMID 19794912, 2009). "MTUS1/ATIP is one of the candidate tumor suppressor genes located in 8p22-p21.3, a region identified in our previous study as one of the most frequent LOH (87.9%) sites in oral cancer." (PMID 25885343, 2015).
squamous cell carcinoma of the tongue (3 papers, 2015 to 2023). "Similarly, decreased MTUS1 expression may be associated with advanced oral tongue SCC." (PMID 37627097, 2023). "Our recent studies also suggest that the down-regulation of MTUS1/ATIP is a frequent event in tongue squamous cell carcinoma (TSCC) and also correlated with poor differentiation and associated with reduced overall survival." (PMID 25885343, 2015).
CNS cancers (2 papers, 2021 to 2022). "Although we have not explored the involvement of the complete renin-angiotensin system in our study, we showed that the MTUS1/ATIP1 serves as a TSG also in glioma." (PMID 33809019, 2021). "In the present study, we demonstrate that MTUS1/ATIP1 expression is reduced or lost in high-grade glioma (HGG) tissue and patient-derived low passage glioma sphere cultures (GSC)." (PMID 33809019, 2021). "The ATIP1-mediated inhibition of proliferation and motility of glioma cells seems to be regulated by ERK and AKT since phosphorylation of ERK1/2 and AKT was strictly inhibited in ATIP1 cells, but was dramatically upregulated after knocking down MTUS1." (PMID 33809019, 2021). "Additionally, in glioma, MTUS1/ATIP1 is a prognostic marker since its expression correlated well with glioma malignancy and survival." (PMID 33809019, 2021). "Using the R2 database as well as the Indian cohort of glioma patients, we also determined whether in glioma patients there are age- or gender-specific differences in MTUS1/ATIP1 expression." (PMID 33809019, 2021). "Glioma specimen, cells and low passage GBM sphere cultures (GSC) were analyzed for MTUS1/ATIP1 expression at the RNA and protein level." (PMID 33809019, 2021). "In glioma cell lines, glioma sphere cultures (GSC), high-grade glioma (HGG) and especially in glioma recurrence, MTUS1/ATIP1 expression is downregulated, probably by promoter hypermethylation." (PMID 33809019, 2021). "MTUS1/ATIP1 was downregulated in high-grade glioma (HGG), GSC and GBM cells and hypermethylation at the ATIP1 promoter region seems to be at least partially responsible for this downregulation." (PMID 33809019, 2021). "Our findings support that in GBM, MTUS1/ATIP1 acts as a TSG, and we believe that a detailed elucidation of the role of MTUS1/ATIP1 in GBM might help to develop new strategies that target MTUS1/ATIP1-associated pathways and that might help to slow down or even block the progression of glioma." (PMID 33809019, 2021). "To understand the mechanisms responsible for its high malignancy and obligatory recurrence, we examined the impact of MTUS1, a tumor-suppressor gene (TSG), coding for ATIP1, in glioma malignancy as well as how its expression might influence glioma therapy." (PMID 33809019, 2021). "In glioma-bearing mice, elevated MTUS1/ATIP1 expression prolonged their survival." (PMID 33809019, 2021). "Besides, in addition to the downregulation of MTUS1 in HGG and recurrent gliomas, MMS2 is also downregulated in these tumors." (PMID 33809019, 2021). "However, there is no information about MTUS1 being an important TSG also in glioma." (PMID 33809019, 2021).
invasive breast carcinoma (2 papers, 2009 to 2023). A carcinoma that infiltrates the breast parenchyma. "We report here for the first time that ATIP3 is the major MTUS1 isoform whose expression is altered in invasive breast cancer." (PMID 19794912, 2009).
lymphoma (2 papers, 2012 to 2022). A malignant (clonal) proliferation of B- lymphocytes or T- lymphocytes which involves the lymph nodes, bone marrow and/or extranodal sites. "MTUS1 down-regulation is now well-described in a wide range of tumor tissues, but to date there have been no studies on MTUS1 involvement in lymphoproliferative diseases like lymphoma." (PMID 22200760, 2012).
MALT lymphoma (2 papers, 2012 to 2021). An indolent, extranodal type of non-Hodgkin lymphoma composed of small B-lymphocytes (centrocyte-like cells). "The specific glycopeptides and glycosylation sites of MTUS1 may play an important role in the development of MALT lymphoma." (PMID 34476221, 2021). "MTUS1 gene has not yet been reported to be mutated or translocated in MALT lymphoma, but its interaction partner AT2R and the RAS were recently described in various aspects of inflammation, including the NF-κB pathway." (PMID 22200760, 2012). "In this study, stable glycopeptides of the MTUS1 protein were found in host cells and host cells infected by MALT lymphoma isolates, but these glycopeptides did not express or exhibite specific glycopeptides in host cells infected by other H. pylori isolates." (PMID 34476221, 2021).
urothelial carcinoma (2 papers, 2014 to 2022). A malignant neoplasm derived from the transitional epithelium of the urinary tract (urinary bladder, ureter, urethra, or renal pelvis). "In this cohort, there was also a significant correlation of MTUS1 expression and histological subtype: positive expression was detected in all micropapillary tumours and aberrant nuclear staining was detected in a subset of plasmocytoid urothelial carcinomas." (PMID 24650297, 2014).
anemia (1 paper, 2012). A reduction in the number of red blood cells, the amount of hemoglobin, and/or the volume of packed red blood cells. "Forty-three percent of the MTUS1 KO mice revealed multiorgan lymphoid hyperplasia affecting spleen (20%), kidney (37%), lung (23%), lymph nodes (17%), and liver (17%) accompanied with leukocytosis, lymphocytosis, and mild anemia." (PMID 22200760, 2012). "Forty-three percent of the MTUS1 KO mice revealed lymphoid hyperplasia affecting spleen (20%), kidney (37%), lung (23%), lymph nodes (17%), and liver (17%) accompanied with leukocytosis, lymphocytosis, and mild anemia." (PMID 22200760, 2012).
ascending aortic aneurysm (1 paper, 2025). "The association between the identified MTUS1 variant and the underlying heart condition (ascending aortic aneurysm) in the patient’s father is unclear." (PMID 40004439, 2025).
autoimmune disease (1 paper, 2012). A disorder resulting from loss of function or tissue destruction of an organ or multiple organs, arising from humoral or cellular immune responses of the individual to their own tissue constituents. "These MTUS1 KO mice can therefore serve as a model for further investigations in cardiovascular disease, autoimmune disease and carcinogenesis." (PMID 22200760, 2012). "To date, nothing is known about the effects of MTUS1 in hematopoiesis or autoimmune disease like SLE, but the reported interaction with AT2R could be a hint for similar effects than the RAS pathway." (PMID 22200760, 2012). "Therefore, MTUS1 KO mice further support the hypothesis of an anti-proliferative effects of MTUS1 and can serve as a model for further investigations in autoimmune disease, cardiovascular disease and carcinogenesis." (PMID 22200760, 2012).
bladder tumours (1 paper, 2014). "In the advanced bladder tumour cohort 45.8% of the tumours (108/236) showed loss of MTUS1 expression and 54% (128/236) tumours were classified into IRS group 1–12." (PMID 24650297, 2014). "In future experiments we want to determine the expression level of potential MTUS1-binding microRNAs and analyse promoter methylation and mutation status of MTUS1 in bladder tumour specimen." (PMID 24650297, 2014). "Additionally, MTUS1 appears to play a major role in two variants of rare advanced and very aggressive bladder tumours." (PMID 24650297, 2014). "In immunohistochemical analysis we found that MTUS1 expression was lost in 50.6% of all papillary and in 45.8% of all advanced bladder tumours." (PMID 24650297, 2014). "Kaplan-Meier analysis revealed significantly better overall (p = 0.029) and disease-specific (p = 0.027) survival for patients with MTUS1 expression in the bladder tumour (IRS 1–12)." (PMID 24650297, 2014).
cataract (1 paper, 2025). Partial or complete opacity of the crystalline lens of one or both eyes that decreases visual acuity and eventually results in blindness. "The role of the MTUS1 variant in cataracts is not known, although, in mouse embryogenesis, multiple isoforms of MTUS1 are expressed in different parts of the developing eye and in the vasculature around the eye, indicating a possible role of MTUS1 in eye pathologies." (PMID 40004439, 2025).